MMP2 (matrix metallopeptidase 2)
Diseases named in the same sentence as MMP2 in open-access papers (continued):
Sharing a sentence is not in itself a finding about the gene and the disease.
tumor (continued). "Matrix metalloproteinases (MMPs), particularly MMP-2 and MMP-9, play a critical role in cancer progression by degrading the extracellular matrix, thereby facilitating tumor growth and metastasis." (PMID 40563423, 2025). "Another study has shown that high doses of melittin attenuated the mRNA and protein expression of MMP-2 and MMP-9 in osteosarcoma 143 B cells, leading to reduced tumor metastasis." (PMID 40141020, 2025). "The expression levels of Ki67, MMP2, and MMP9 in tumor tissues were determined via immunohistochemical (IHC)." (PMID 39944827, 2025). "M2-TAMs release various proteolytic enzymes, including MMP2 and MMP9, which facilitate ECM breakdown and tumor progression." (PMID 40670983, 2025). "Through the production of matrix metalloproteinases (MMPs), such as MMP2 and MMP9, CAFs break down ECM barriers, facilitating tumor cell migration and invasion." (PMID 39940643, 2025). "For instance, CAFs expressing MMP2 interact with tumor cells via THBS2, enhancing extracellular matrix degradation and tumor cell motility." (PMID 39950116, 2025). "MMP2, COL6A3, PRRX1, COL1A2, GREM1 and SNAI2 are integral to the EMT process, a key driver of metastasis that allows tumor cells to detach and invade distant tissues." (PMID 39920655, 2025). "Such mass spectrometry-based proteomics-driven discoveries have expanded the CTX interactome beyond MMP-2, ClC-3, and annexin A2, highlighting neuropilin-1 (NRP1) as another critical binding partner for tumor selectivity." (PMID 41155199, 2025). "Matrix metalloproteinases (MMPs), particularly MMP-2 and MMP-9, are Zn2+-dependent endopeptidases that degrade ECM structural components, facilitating tumor dissemination and invasion." (PMID 40940940, 2025). "The dendrimer-based probe, integrating a matrix metalloproteinase-2 (MMP-2)-responsive green fluorescence probe, exhibited heightened signals specifically from tumor cells." (PMID 41048541, 2025). "Specifically, we propose that SP influences MMP-9 and MMP-2 activity, thereby facilitating ECM remodeling, tumor invasion, and metastasis." (PMID 40321254, 2025). "Among them, MMP2 and MMP9 are also known as type IV collagenases, which are the most commonly expressed MMPs in tumor cells and are highly expressed in digestive system tumors." (PMID 40563539, 2025). "Microglia enhance tumor cell invasion through the secretion of TGF‐β and regulation of MMP2, which degrades the extracellular matrix (ECM)." (PMID 40104956, 2025). "IHC was used to analyze the levels of Ki67, MMP-2, MMP-9, and Cleaved-caspase 3 proteins in each group’s tumor tissues." (PMID 39508798, 2025). "Based on this, an MMP2-activated and ATB0,+-targeted liposome with doxorubicin and sorafenib (DS@MA-LS) was developed to treat 4T1 tumor cells." (PMID 40837737, 2025). "Derivatives like FLLL32 degrade STAT3, suppressing tumor angiogenesis (VEGF) and metastasis (MMP-2/9) in preclinical osteosarcoma models." (PMID 40918117, 2025). "Data generated from our studies clearly demonstrated that Spry1KO led to the down-regulation of several MMPs, including MMP-2, MMP-3 and MMP-8, which have been recently explored as targets to hamper cancer angiogenesis and, in turn, tumor cell dissemination." (PMID 39953610, 2025). "Although more than 10 miRNAs can suppress tumor migration and invasion by regulating MMP-2 and MMP-9, only miR-29b directly targets MMP-2, and only miR-491-5p directly targets MMP-9." (PMID 41356146, 2025).
tumor (continued). "A key aspect of cancer progression involves the remodeling of the extracellular matrix, a process largely mediated by matrix metalloproteinases (MMPs) such as MMP2 and MMP9, which facilitate tumor invasion and metastasis." (PMID 40136519, 2025). "MMP2 and MMP9 mediate important steps in tumor angiogenesis by degrading ECM and basement membrane (BM), creating a conducive environment for the generation and extension of new blood vessels." (PMID 39781344, 2025). "Sevoflurane inhibits miR-155 expression and reduces the expression of MMP-2 and MMP-9, which in turn limits tumor cell migratory invasion and induces apoptotic cell death in tumor cells." (PMID 40565017, 2025). "Invadopodia of tumor cells are rich in MMP2 and MMP9, and these protrusions serve as crucial structures enabling tumor cell invasion." (PMID 41463642, 2025). "During brain metastasis, the CA IX/MMP-2 axis disrupts the tight junction proteins of the blood–brain barrier and the ECM, facilitating the intracranial migration of tumor cells." (PMID 40422196, 2025). "H&E and IHC staining revealed decreased staining for CYR61, MMP‐2, and YAP in tumor sections from mice bearing the ZDHHC15‐depleted cells." (PMID 39686664, 2025). "Tumor-derived EVs are especially rich in oncoproteins (eg, mutant KRAS, MET) and proteases (MMP2/9), which contribute to invasive and metastatic properties." (PMID 40959053, 2025). "L. plantarum YYC-3 has demonstrated remarkable efficacy in suppressing CRC cell growth, invasion and migration, significantly reducing the expression of key genes like MMP2, MMP9 and VEGFA that are crucial for tumor angiogenesis and metastasis." (PMID 40520902, 2025). "For example, in tumor growth and dissemination, STAT3 activation controls FAK phosphorylation and MMP-2 activity." (PMID 40217305, 2025). "In the colon-derived cells, during the transition from a healthy to a tumor cell and then to a metastatic cell type, we observed a gradual increase in the EMT-TF genes SNAI2 and ZEB1, and in VIM, CDH5 and MMP2." (PMID 40332096, 2025). "Activated fibroblasts can secrete more cytokines such as MMP-2, TGF-β, SDF-1, and IL-6 for extracellular matrix (ECM) remodeling and tumor progression." (PMID 40707430, 2025). "IF1 expression levels were positively related to those of VE-cadherin, vimentin, MMP2, and MMP9, while they were negatively related to E-cadherin, indicating that IF1 can promote tumor progression by enhancing the EMT and VM formation." (PMID 41306771, 2025). "Consistently, Ki67, MMP2, MMP9, c-Myc, β-catenin, CDK4, CDK6, and Cyclin D1 protein levels in tumor tissues were significantly decreased by SAMD5 overexpression but partially increased by PLK1 overexpression." (PMID 39524172, 2024). "Matrix metalloproteinase 2 (MMP2) and 9 (MMP9), cathepsin, CCL18, and CYP4A promote extracellular matrix (ECM) breakdown and stimulate tumour dissemination." (PMID 38920685, 2024). "MMP2 and MMP9 play important roles in tumor invasion and metastasis by degrading collagen fibers cleaved by collagenase." (PMID 38429828, 2024). "RA was observed to decrease cells’ invasive abilities by inhibiting MMP-2 and MMP-9 in several tumor cell lines." (PMID 39519255, 2024). "Main mast cells mediators have been described in the tumor microenvironment, including chymase, tryptase, VEGF, Histamine, TNF-α, MMP2, MMP-9, TIMPs, NGF, and sphingosine-1-phosphate." (PMID 38969910, 2024). "Mechanistically, PDAC with high expression of MMP-2 will propel the as-prepared nanovesicle to dwell in tumor region via shedding PEG on the nanovesicle surface, effectively enhancing tumor uptake." (PMID 38755645, 2024). "Leptin can regulate other factors and pathways affecting bone resorption, such as matrix MMP2 and MMP9, which are involved in extracellular matrix remodeling, tumor progression, and bone absorption." (PMID 38571500, 2024).
tumor (continued). "The majority of M2 subtypes are anti-inflammatory and pro-angiogenic, secreting growth factors (VEGF, PDGF) and matrix metalloproteinases (MMP2, MMP9) which boost tumor growth, metastasis, and invasion." (PMID 38935134, 2024). "PFP@PDM-PEG efficiently accumulated in tumor tissues where VM is prone to occur and then the PEG group was shed in response to hydrolysis by MMP-2 present in high levels in the tumor ECM, leading to enhanced tumor cell uptake." (PMID 38664830, 2024). "Previous studies have reported that MMP2, MMP9 and TWIST are important functional proteins involved in VM formation in tumor cells." (PMID 39050762, 2024). "Western blot analysis revealed that melittin significantly reduced the expression levels of MMP2 and MMP9 in a dose-dependent manner, indicating impaired tumor cell movement, consistent with the results from wound-healing and transwell assays." (PMID 39519238, 2024). "Based on previous data results, our study conducted systematic subgroup analysis of MMP1-1607 2G/1G, MMP2-1306 T/C, MMP2-735 T/C, MMP7-181 G/A, MMP9-1562 T/C, and added the analysis of tumor-related factors in some public databases." (PMID 38762659, 2024). "MMP-2 and MMP-9 play vital roles in tumor invasion due to their potent ability to degrade collagen type IV." (PMID 38827318, 2024). "Curcumin has been reported to inhibit NF-κB expression and the activity of MMP-2 and MMP9, thereby suppressing tumor metastasis and invasion." (PMID 38313314, 2024). "This was supported by decreased expression of matrix metalloproteinases MMP2 and MMP9, which play a role in tumor cell invasiveness and metastasis." (PMID 39796103, 2024). "Specifically, MMP-2 and MMP-9 are pivotal in degrading basement membrane type IV collagen, thereby promoting tumor growth, invasion, and angiogenesis." (PMID 39431222, 2024). "For instance, MMP-2 and MMP-9 have been shown to promote tumor invasion and metastasis in breast cancer by degrading the ECM components and facilitating tumor cell migration." (PMID 39493455, 2024). "Studies indicate that astrocytes play a critical role in modulating the protein and matrix composition of tumor cells by releasing MMP-2 and MMP-9, thereby promoting the invasion and metastasis of tumor cells in the brain." (PMID 38577333, 2024). "In tumors, MMP2 and MMP9 are involved in connective tissue degradation, tumor-induced angiogenesis, and cell migration." (PMID 38541002, 2024). "It was found that the MMP-2 and MMP-9 levels in tumor tissue, epinephrine and norepinephrine levels in serum, and the tumor volume were significantly higher in the stressed group than in the non-stressed group." (PMID 39335164, 2024). "In contrast to claudin-1, meta-analysis suggests that MMP-1, MMP-2, MMP-9, and VEGF are highly expressed in RB, which are highly correlated with poor cell tumor differentiation, tumor invasion, and clinically advanced stage." (PMID 38920989, 2024). "By liberating vascular endothelial growth factor (VEGF) from angiogenic islets, MMP-9 is known to initiate the angiogenic migration in cancer, whereas MMP-2 controls the bioavailability of dissolved VEGF-A and tumor vascular patterning." (PMID 38672151, 2024). "Specifically, it has been demonstrated to downregulate the expression and activity of MMP-2 and MMP-9, key enzymes involved in extracellular matrix degradation and tumor invasion." (PMID 38939095, 2024). "COL1A1 can enhance the activity of MMPs, particularly MMP2, which degrade the ECM and facilitate tumor cell invasion and metastasis." (PMID 39065771, 2024). "Among the members of the MMP family, MMP-2 and MMP-9 are known to play a direct role in tumor metastasis." (PMID 39364049, 2024). "In cancer cells, GOLM1 has the ability to be released into the cytoplasm and acts as a molecular chaperone to interact with various tumour‐related molecules such as EGFR, RTK, MMP2, MMP7 and B3‐H7, exerting a pro cancer effect." (PMID 39470578, 2024).
tumor (continued). "The elevated expression and activity of MMP-2 and MMP-9 in tumor contexts instigate the breakdown of these basement membranes, a pivotal step in tumor invasion and the metastatic process." (PMID 38939095, 2024). "Gelatinases, specifically MMP-2 and MMP-9, play critical roles in the processes of tumor growth, invasion, and metastasis." (PMID 39858430, 2024). "When the NPs reached the tumor, GPLGIAGQ underwent structural degradation in response to MMP-2, exposing the NPs to interact with the cell." (PMID 39339228, 2024). "MMP2 can degrade most components of the ECM and basement membrane, facilitating the invasion and spread of tumor cells." (PMID 38978899, 2024). "Analysis of the DEGs in TCGA tumours revealed that the miR-18a/low tumours expressed high levels of EMT master regulators-ZEB1 and ZEB2 and Matrix metalloproteinases, MMP2, MMP3, MMP10, MMP11, MMP13 and MMP17 (p < 0.05)." (PMID 38786043, 2024). "In therapy‐induced tumour senescence, there is an enhanced expression of pro‐angiogenic factors (FGF2, VEGF and PDGFA/B) and MMPs (MMP2/3/7/9/10)." (PMID 39270064, 2024). "Sorcin knockdown decreases the expression of matrix metalloproteinases (MMP2 and MMP9), cathepsin Z, and STAT3, leading to suppressed tumor growth and metastasis." (PMID 39199583, 2024). "EGCG inhibits tumor angiogenesis in HUVECs by inhibiting MT1-MMP, which degrades collagen type I and subsequent MMP-2 activation." (PMID 38611849, 2024). "We found that cysteamine treatment at micromolar concentrations specifically targets MMP2, MMP9, and MMP14, leading to the inhibition of tumor invasion and migration in GBM cells overexpressing these genes." (PMID 38893149, 2024). "Numerous studies have demonstrated abnormal expression of MMP2 and MMP9 in tissues following tumor occurrence." (PMID 38189823, 2024). "As gelatinases, MMP-2 and MMP-9 degrade type IV collagen in the basement membrane, contributing to carcinogenic processes such as cell proliferation, angiogenesis, and tumor metastasis when their activity is dysregulated." (PMID 39063556, 2024). "Overexpression of GLUT1 has been shown to enhance the expression of MMP2 and participate in the process that TGF‐β1 induces EMT of tumor cells." (PMID 39092293, 2024). "IHC results illustrated that MMP2 and MMP9 expression in tumor tissue was suppressed by Oct4 knockdown." (PMID 38430256, 2024). "Degradation of stromal collagen by MMP-2 and MMP-9 is the biochemical basis for tumor cell migration and invasion into surrounding tissues." (PMID 38776295, 2024). "MMP-2, MMP-9, and MMP-14 can be upregulated in some types of tumor cells through a hypoxia-inducible factor (HIF)-dependent mechanism." (PMID 39408814, 2024). "The treatment decreased MMP-2 and MMP-7 mRNA expression, reduced VEGF protein expression, and downregulated the ERK and PI3 K/Akt pathways in the tumor tissue, attenuating the metastatic ability of the cancer cells." (PMID 39335164, 2024). "Upon adherence to tumor endothelial cells, MSC secretes matrix metalloproteinases 2 (MMP-2) matrix protease to mediate their migration." (PMID 39267776, 2024). "Among them, MMP-2 and MMP-9 blocked the expression of tight junction proteins claudin-5 and ZO-1, thus helping tumor cells to cross the BBB." (PMID 38243240, 2024). "In tumor tissues, overexpression of miR-22 also diminished the expression of NLRP3, MMP-2, and MMP-9 compared with the model group." (PMID 39858430, 2024). "The transcription levels in tumor tissues of related proangiogenic cytokines or chemokines such as SDF-1, MMP-2, MMP-9, and VEGFR2 treated with CPA or 5-Fu were also determined using RT-PCR." (PMID 39119610, 2024). "Reduced MMP-2 and MMP-9 expression was noted in the tumor tissue, inhibiting the invasion and metastasis of neoplastic cells." (PMID 39335164, 2024).
tumor (continued). "Analysis from the acquired immunofluorescence pictures revealed that PTGS2, MMP9, MMP2, and CXCR 4 were mostly located around the nucleus in tumor tissues, and PPARG was mostly located inside the nucleus in tumor tissues." (PMID 38457601, 2024). "Our findings revealed a mechanistic link between CCZ1 and MMPs, particularly MMP2 and MMP17, which are known regulators of tumor invasion and metastasis." (PMID 39062041, 2024). "MMP2 and MMP9 play a crucial role in tumor cell invasion and metastasis by degrading the basal membrane." (PMID 39343952, 2024). "This analysis prompted a focus on specific MMPs more distinctly expressed in CC2, such as MMP2, MMP9, MMP11, MMP14, and MMP25, suggesting their potential role in tumor invasion and their clinical relevance as potential therapeutic targets." (PMID 38893149, 2024). "MMP2, a member of the Matrix metalloproteinases family, was positively correlated with MICAL2, confirming that MICAL2 shows potential for promoting tumor metastasis by degrading the ECM." (PMID 38326344, 2024). "Studying their effect on Hh signaling as well as on the expression of MMP-2 and MMP-9, which are involved in tumor progression, is interesting from the point of view of creating drugs with antitumor activity that can be used in various types of human cancer." (PMID 39274874, 2024). "In cancer, the overproduction or increased activity of MMP2/9 leads to the degradation of ECM and BM, thereby facilitating tumor cell invasion and metastasis to distant organs." (PMID 39057404, 2024). "This vaccine elicited auto-antibodies against MMP-2, with CD4+ T cells identified as pivotal in driving the anti-tumor response." (PMID 39081320, 2024). "The activities of MMP-2 and MMP-9 increased by 60% and 84%, respectively, and were much higher in tumor than in control brain tissue (p < 0.0001)." (PMID 38275897, 2024). "α‐solanine treatment inhibited MMP‐2/9 mRNA expression in human choriocarcinoma cells (JEG‐3 cells) and reduced MMP‐2 activity, suggesting that α‐solanine inhibits tumor cell metastasis." (PMID 39155844, 2024). "Western blotting revealed lowered expression levels of PCNA, MMP2, MMP9, and VEGF, providing additional evidence for the anti-tumor efficacy of ZSTK474." (PMID 39466763, 2024). "A study showed that nimbolide prevented metastasis and tumor invasion by inhibiting PMA-induced phosphorylation of ERK1/2 and MMP-2/9 expression." (PMID 38571915, 2024). "Protein expression levels of SPHK2, metal matrix protease 2 (MMP2), MMP9 and urokinase-type plasminogen activator (uPA) in tumor tissues were assessed by immunohistochemistry (IHC)." (PMID 38965120, 2024). "Immature myeloid cells (iMCs) are recruited from the bone marrow to the tumor invasion front express matrix metalloproteinases MMP9, MMP2, and CCR1, migrating toward the Ccl9 expressed by the tumor epithelium in adenocarcinoma." (PMID 39768150, 2024). "Research indicates that MMP-2 and MMP-9 play significant roles in cancer cell proliferation and invasion, impacting tumor growth, aggressive progression, and patient survival in UTUC." (PMID 39063556, 2024). "Arg1 17 and Ym1 18 are fundamental features of M2 macrophages, with the secretion of Arg1 19, Ym1 20, MMP2 21 and MMP9 22 by macrophages promoting the metastasis of tumor cells." (PMID 38356723, 2024). "Human tumor xenografts originating from head and neck (CAL27), lung (A549), and colorectal (HCT116) cancer cells all demonstrated MMP-2/9 activity." (PMID 39683778, 2024). "In order to validate the effect of CCNL1 on the progression and ADM-resistant of OS cells, we explored the expression levels of tumor-related genes MRP1, Survivin, and MMP2 in CCNL1-overexpressing HOS and 143B cells." (PMID 39024509, 2024).